PPP1R7 (protein phosphatase 1 regulatory subunit 7)
Description:
Regulatory subunit of protein phosphatase 1.
Synonyms: SDS22
Tractability: PROTAC: ubiquitination databases record sites on it; its protein half-life has been measured.
Gene: Protein-coding gene on chromosome 2 (241,149,576 to 241,183,652, forward strand). Ensembl gene ENSG00000115685.
Subcellular location: Nucleus
Subcellular location (Human Protein Atlas): Nucleoli
Gene Ontology:
Molecular function: protein binding; protein phosphatase regulator activity; enzyme regulator activity
Biological process: chromosome segregation
Cellular component: chromosome; extracellular exosome; nucleus; cytoplasm
Genetic constraint (gnomAD): Loss-of-function variants: 14 observed, 40.38 expected, observed/expected ratio (o/e) 0.35, 90% interval 0.23 to 0.54. The upper end of that interval is the gene's LOEUF score, 0.54, which puts it in group 2 of 6, group 1 being the genes least tolerant of losing a copy. Missense variants: 310 observed, 459.51 expected, observed/expected ratio (o/e) 0.67, 90% interval 0.61 to 0.74. Synonymous variants: 179 observed, 189.3 expected, observed/expected ratio (o/e) 0.95, 90% interval 0.84 to 1.07.
Homologues: Orthologues: chimpanzee PPP1R7 (99% identical), guinea pig PPP1R7 (95% identical), rat Ppp1r7 (95% identical), dog PPP1R7 (85% identical), pig PPP1R7 (73% identical), zebrafish ano7 (20% identical). Paralogues in human: ANO3 (25% identical), ANO1 (23% identical), ANO5 (23% identical), ANO6 (23% identical), ANO4 (23% identical), ANO2 (22% identical), ANO7 (22% identical), ANO8 (21% identical), ANO9 (19% identical), ANO10 (18% identical).
Diseases named in the same sentence as PPP1R7 in open-access papers:
PPP1R7 is named in the same sentence as 17 diseases in open-access papers, as found by Europe PMC text mining. Sharing a sentence is not in itself a finding about the gene and the disease. The quoted sentences say what the papers report.
breast carcinoma (1 paper, 2022). "An in vitro study has shown that PPP1R7 can induce apoptosis and, consequently, inhibit breast cancer tumorigenesis, mainly through the negative regulation of the AKT signaling pathway." (PMID 36011278, 2022).
HCMV infection (1 paper, 2024). "Our findings indicate that HCMV infection disrupts PP1 function through the temporal dysregulation of at least nine recognized regulatory subunits, PPP1R10, PPP1R7, YLPM1, PPP1R11, PPP1R9A, PPP1R8 (NIPP1), PPP1R9B, PPP1R12C, and URI1." (PMID 39772267, 2024).
oral squamous cell carcinoma (1 paper, 2022). "PPP1R7 has been reported to be a tumor suppressor gene, since the allelic loss of 2q37, where this gene is seated, is associated with oral squamous cell carcinoma." (PMID 36011278, 2022).
cancer (4 papers, 2009 to 2024). A tumor composed of atypical neoplastic, often pleomorphic cells that invade other tissues. "SCIN, LRP1B, CPNE3, TICRR, and PPP1R7 are connected to cancer cell invasion, migration, proliferation, and apoptosis." (PMID 37628788, 2023). "Other mRNAs such as BARX1, EIF3D, PPP1R7, and HSD17B1 are also known to be associated with different cancers or other diseases." (PMID 29270229, 2017).
tumor (3 papers, 2009 to 2022). "Thus, downregulation of Sds22/PPP1R7 may contribute to tumour progression in humans." (PMID 19228425, 2009).
hematologic malignancies (1 paper, 2022). "PPP1R7 protein also plays an important role in accurate chromosome segregation, although the association between the PPP1R7 protein and carcinogenesis/tumorigenesis, especially leukemogenesis in hematologic malignancies, generally remains unknown." (PMID 36011278, 2022).
PPP1R7 also shares sentences with these, for which no sentence is quoted: acute myeloid leukemia (1 paper); acute promyelocytic leukemia (1); autism spectrum disorder (1); colorectal carcinoma (1); HIV-1 infection (1); influenza infection (1); melanoma (1); neurodevelopmental disorder (1); ovarian carcinoma (1); prostate carcinoma (1); squamous cell carcinoma (1).